CHI3L1 (chitinase 3 like 1)
Diseases named in the same sentence as CHI3L1 in open-access papers (continued):
Sharing a sentence is not in itself a finding about the gene and the disease.
infection (continued). "A correlation between elevated serum levels of Chi3L1 and infection with Streptococcus pneumoniae was reported >10 years ago." (PMID 25595947, 2015). "It has long been known that Chi3L1 is specifically upregulated in inflammatory conditions of the gut, and infection studies have suggested a function in both development and resolution of intestinal inflammation as well as bacterial clearance." (PMID 25595947, 2015). "Up-regulated gene expression of four AMPs (Chi3l1, Cxcl17, Lcn2, Spli) was found in the lungs during the whole course of infection." (PMID 25137043, 2014). "CHI3L1 levels increased with age in both areas but were significantly higher in the high infection areas compared to the low infection area." (PMID 23145202, 2012). "Comparing villages of different endemicity allows a comparative approach separating the effects of history of schistosome infection from current infection levels, both factors that can potentially influence CHI3L1 levels." (PMID 23145202, 2012). "Our study investigated CHI3L1 in a single infection setting; it will be interesting to see if the same relationship with infection status pre- and post- treatment is also observed in S. mansoni infection where there is no existing marker for early morbidity." (PMID 23145202, 2012). "Taken together these observations suggest that CHI3L1 levels are related to current levels of infection." (PMID 23145202, 2012). "Older individuals have had a lifetime of exposure to infection, and may be experiencing more advanced pathology associated with inactive disease including bladder calcification and a drop in egg excretion, as well as a higher background level of CHI3L1 associated with age." (PMID 23145202, 2012). "Other factors confounding the relationship between CHI3L1 and infection status pre- and post- antihelminthic treatment, such as the onset of age-related diseases requires further investigation." (PMID 23145202, 2012). "CHI3L1 gene expression is induced during infection, manifesting in dual action against pathogens: promotion of bacterial clearance and augmentation of host defense, and CHI3L1 knock-out mice demonstrated more severe bacterial infection and ameliorated response to allergens." (PMID 38125621, 2024). "Chi3l1-/- mice, which make attenuated allergic responses, did not manifest impaired clearance of the nematode Nippostrongylus brasiliensis (Nb) during early neutrophil-mediated stages of infection, in spite of reduced lung IL-17A levels." (PMID 37575256, 2023). "Here, we demonstrate that CHI3L1 augments epithelial cell infection by pseudoviruses that express the alpha, beta, gamma, delta, or omicron S proteins and that the CHI3L1 inhibitors anti-CHI3L1 and kasugamycin inhibit epithelial cell infection by these VOC pseudovirus moieties." (PMID 35735790, 2022). "Intriguingly, it may be required an older age and/or the presence of infection for detecting increased expression of CHI3L1 despite the increased protein levels in the CSF of AD patients." (PMID 33584248, 2020). "The infection promoting effects have been found to stem from enhanced adhesion of bacteria to intestinal epithelial cells (IECs), specifically through bacterial interaction with N-glycosylation patterns on Chi3L1 expressed by IECs." (PMID 25595947, 2015). "Overall, our study has demonstrated that CHI3L1 levels are associated with schistosome infection status regardless of cumulative history of exposure to infection." (PMID 23145202, 2012). "Our results are consistent with this observation in that it was infection status rather than intensity that was associated with CHI3L1 levels." (PMID 23145202, 2012). "Furthermore, in order to resolve the mechanism behind the observed elevation as well as the relationship between CHI3L1 levels and infection status in the different age groups mechanistic studies on both human and mouse models will be required." (PMID 23145202, 2012).
infection (continued). "The significant interaction between age and infection status with the difference between schistosome-infected and uninfected people being the most apparent in the youngest age group is consistent with a dynamic relationship between infection status and CHI3L1 levels as people age." (PMID 23145202, 2012). "A recent study indicated that both chi3l1 and perlucin-like genes were significantly down-regulated in L. vannamei following WSSV infection." (PMID 40723597, 2025). "Our studies demonstrate that cellular infection with SC2, in its ancestral and VOC forms, is diminished by anti-CHI3L1 and kasugamycin." (PMID 35735790, 2022). "The present studies add to our understanding of the therapies for the early phase of SC2 by demonstrating that the inhibition of ChI3L1 with FRG and/or kasugamycin ameliorates cellular infection induced by the alpha, beta, gamma, delta, and omicron SC2 VOC." (PMID 35735790, 2022). "Our studies demonstrate that CHI3L1 is a major stimulator of ACE2 and SPP that enhances SC2 S protein–receptor binding and activation — and augments SC2 infection and spread." (PMID 34747367, 2021). "Based on these observations, one would expect that SC2 infection and subsequent RLH activation would decrease the levels of circulating CHI3L1." (PMID 34747367, 2021). "On day 3 after infection, the BALF of the CTX-IPA and HC-IPA groups had high levels of CHI3L1 (vs. the control group, p < 0.05)." (PMID 33468116, 2021). "CHI3L1 was overexpressed in SW620 and HCT116 by lentiviral technology, and the cell infection rate was 98% from the fluorescence results." (PMID 31536166, 2020). "CHI3L1 levels were higher among children with CM and SMA who subsequently went on to die of their infection, compared to survivors in their respective groups (p < 0.01)." (PMID 25047113, 2014). "Therefore, we conclude that CXCR5 expression by the TH2 priming cDC2 subset supports upregulation of Chi3l1, and Chi3l1 can, in turn, function as a DC-derived secretory factor to support protective TH2 responses following infection." (PMID 41012147, 2025). "While Chi3l1 was critical for IgE humoral responses it was not required for vaccine or infection-induced IgG1 responses." (PMID 37575256, 2023). "Thus, Chi3l1 regulates the magnitude of TFH and antigen-specific B cell responses to both infection and immunization." (PMID 37575256, 2023). "However, following infection, obese mice had increased circulating levels of B cell activating factor (BAFF, p = 0.0070), CCL5 (p = 0.0118), CCL17 (p = 0.0118), Chitinase-3-like 1 (p = 0.0118), CXCL5 (p = 0.0118), and IFN-alpha (p = 0.0118)." (PMID 32854687, 2020). "Interestingly, CHI3L1 was equally induced at 24 h p.i. by both these MPEC strains, although infection with E. coli P4 yielded significantly higher bacterial loads, IL-8 levels, and subsequent neutrophil recruitment compared to E. coli 1303 infection." (PMID 29892291, 2018). "Accordingly, the change in CHI3L1 on clearing infection was not related to pre-treatment infection intensity (data not shown)." (PMID 23145202, 2012). "To determine if CHI3L1 levels differ in people with visible signs of pathology, we compared levels of the protein in children who had visible haematuria to age and infection intensity matched controls confirmed negative for haematuria." (PMID 23145202, 2012). "Correlating the extracted PCs from the factor analysis with CHI3L1 while controlling for sex, age group, infection area, and infection status revealed a negative association between PC2 and CHI3L1 levels (r = −0.184, p = 0.037)." (PMID 23145202, 2012). "Strangely, no significant changes in CHI3L1 mRNA were observed in young AD patients with severe symptoms, which makes us wonder if the increase in CHI3L1 expression in AD requires age-related synergy or infection." (PMID 38003338, 2023). "Interestingly, infection intensity, when analysed in the same model, did not significantly affect CHI3L1 levels (F1,858 = 2.016, p = 0.156)." (PMID 23145202, 2012).
infection (continued). "Since the Nb study did not measure TH2 or IgE responses following Nb infection, we used the helminth Heligmosomoides polygyrus bakerii (Hp) to address whether Chi3l1 is required for type 2 immunity in the setting of a strong TH2-driven enteric helminth infection." (PMID 37575256, 2023). "Thus, Chi3l1 modulates ICOS expression by Hp-infection elicited TFH cells but not TREG cells." (PMID 37575256, 2023). "CHI3L1 similarly enhanced the cellular integration of pseudovirus containing S sequence with D614 or G614, and FRG treatment inhibited pseudoviral infection regardless of S sequence." (PMID 34747367, 2021). "However, one can also see how CHI3L1-based therapeutics that inhibit ACE2 and SPP can inhibit SC2 infection regardless of the S protein sequence." (PMID 34747367, 2021).
neurodegenerative disease (44 papers, 2010 to 2025). A disorder of the central nervous system characterized by gradual and progressive loss of neural tissue and neurologic function. "However, in the context of neurodegenerative diseases, the expression of CHI3L1 is often dysregulated, leading to its association with neuroinflammation, glial activation, and neuronal damage." (PMID 39827337, 2025). "These variations in CHI3L1 levels across studies highlight potential differences in the inflammatory responses between PD, AD, and other neurodegenerative diseases, underscoring the need for further research into CHI3L1’s role in PD." (PMID 39827337, 2025). "In neurodegenerative diseases, CHI3L1-RAGE interactions influence neurogenesis by affecting neural stem cell proliferation and differentiation." (PMID 39768177, 2024). "CHI3L1 in serum can be used as a supportive biomarker in neurodegenerative diseases." (PMID 40495463, 2025). "This review addresses the complexities of targeting CHI3L1, highlights its potential in precision medicine, and outlines future research directions aimed at unlocking its full therapeutic potential in treating neurodegenerative diseases and brain pathologies." (PMID 39827337, 2025). "Since we found elevated CHI3L1 levels in the CSF of a variety of neurological and neurodegenerative diseases, we wanted to study whether CHI3L1 expression is prevalent in astrocytes in those conditions." (PMID 20540736, 2010). "The increase in secreted protein levels like chitinase 3 like 1 (CHI3L1) and osteopontin (SPP1) was observed in patients with pathology of AD and neurodegenerative disease." (PMID 36793451, 2023). "CHIT, CHI3L1, and CHI3L2 have received significant attention from both clinical and biological perspectives concerning inflammation-prone brain diseases, and they are now recognized as markers of neuroinflammation across a spectrum of neurodegenerative diseases." (PMID 38785530, 2024). "Previously, CHI3L1 expression was shown to be up-regulated in inflammatory conditions, but apart from one report of increased CHI3L1 mRNA in AD brain, there were no data in the literature characterizing the cellular source of CHI3L1 in neurodegenerative diseases." (PMID 20540736, 2010).
neurological diseases (40 papers, 2010 to 2025). "According to the comprehensive Open Targets Platform and text-mining scores, AD is the neurological disease most strongly associated with the CHI3L1 gene." (PMID 38177294, 2024). "The text-mining score of CHI3L1 (0.919) was the highest score, and the overall association score (0.133) was the second highest score among the neurological diseases." (PMID 38177294, 2024). "This section describes the associations and related target genes of CHI3L1 in neurological diseases." (PMID 38177294, 2024). "CHI3L1 is considered a biomarker in mild stages of MS, and a high level of CHI3L1 in the cerebrospinal fluid is associated with the development of neurological disorders." (PMID 36052093, 2022). "In summary, CHI3L1 expression in MS, aging and other neurological diseases is mostly associated with astrocytes." (PMID 20540736, 2010). "Taken together, these findings demonstrate that CHI3L1 is induced in astrocytes in a variety of neurological diseases but that it is most abundantly associated with astrocytes in regions of inflammatory cells." (PMID 20540736, 2010). "In addition, ALS and SCZ are also associated with the CHI3L1 gene in the neurological disease category." (PMID 38177294, 2024). "CHI3L1 has been recognized as a prominent biomarker in neurological disorders marked by neuroinflammation, including autoimmune diseases such as NMO spectrum disorder (NMOSD)." (PMID 39827337, 2025). "CHI3L1 was significantly upregulated in Group 1 monocytes and its expression is upregulated in neurological diseases such as MS and AD." (PMID 40051633, 2025). "This section provides a comprehensive discussion of CHI3L1’s involvement in various neurological diseases, offering insights into its pathological mechanisms and therapeutic implications." (PMID 39827337, 2025). "The intricate interactions of the immune system with the brain hold significant therapeutic potential in neurological diseases, and CHI3L1 has emerged as a promising therapeutic target in this context." (PMID 38177294, 2024). "Several clinical studies reported that the elevation of CHI3L1 was observed in patients suffering from a wide range of diseases: cancer, metabolic, and neurological diseases." (PMID 33222690, 2020). "Cerebrospinal fluid level of chitinase 3-like 1 (CHI3L1, YL-40) is induced in astrocytes in a variety of neurological diseases." (PMID 27344170, 2016). "In the current study CHI3L1 transcription and expression were evaluated in a variety of acute and chronic human neurological diseases." (PMID 20540736, 2010). "Many studies have shown that Chi3l1 is expressed and secreted by various cell types of the nervous system, such as activated microglia and astrocytes, making it a potential biomarker for neurological diseases." (PMID 39769202, 2024). "Another study representing the first transcriptome sequencing study proposed the association of seven genes (CTSS, SERPINA1, NPTX1, PTX3, CHI3L1, SERPINA3, and MX1) as “the missing link” to explain the correlation between HHV-6A infection and neurological diseases." (PMID 35683449, 2022). "The chitinase family, predominantly chitinase 3-like protein 1 (CHI3L1), has received widespread attention as possible biomarkers in a multitude of neurological disorders, including RRMS, as previously reviewed." (PMID 38527011, 2024). "Both, CHI3L1 and GFAP, are described as markers of astrocyte activation or damage in MS as well as other neurological diseases." (PMID 36142860, 2022). "In conclusion, based upon the results of our comprehensive analysis of HHV-6A infected HA1800 cells, we revealed several genes correlated with neurologic disorders, especially CTSS, PTX3, CHI3L1, Mx1, CXCL16, BIRC3, and BST2 genes." (PMID 27344170, 2016). "Indeed, while the levels of CHI3L1 and CHI3L2 in AD patients tend to increase leading to hypothesis of a potential immunological role, CHID1 levels tend to decrease both with age and in neurological diseases such as AD." (PMID 33924468, 2021).
inflammation (16 papers, 2012 to 2024). Aberrant reaction of the microcirculation characterized by movement of fluid and leukocytes from the blood into extravascular tissues. "Several studies also revealed that fecal CHI3L1 aids in predicting the severity and activity of intestinal inflammation in both pediatric and adult IBD." (PMID 31179321, 2019). "Our results indicate that CHI3L1 and lubricin might be considered as potential natural agents for providing therapeutic protective effects in joint inflammation, and/or may promote cartilage preservation in degenerative disorders of articular cartilage." (PMID 26978347, 2016).
bacterial infection (14 papers, 2009 to 2024). "More recently, a comprehensive study utilizing Chi3L1 KO mouse lines and intratrancheal bacterial infections explored the functional role." (PMID 25595947, 2015). "However, Chi3L1 also promotes clearing and resolution of bacterial infections and inflammation in colitis through Stat3 signaling." (PMID 25595947, 2015). "Out of the 34 miscellaneous biomarkers, 12 biomarkers–c5a, ferritin, hepcidin, CHI3L1, D-dimer, FGF, Gamma-GT, PDGF-BB, SGOT, SGPT, SP-D, and VEGFR-1– did not have any statistically significant data to support their use in differentiating bacterial versus non-bacterial infections." (PMID 27486746, 2016).
adenocarcinoma (8 papers, 2010 to 2024). A common cancer characterized by the presence of malignant glandular cells. "Induction of Stat3C induced downstream genes (including CHI3L1), lung inflammation and adenocarcinoma." (PMID 23613996, 2013).
colorectal (6 papers, 2012 to 2022). "The high expression of CHI3L1 and MVD was significantly correlated with the invasion depth, differentiation degree, vascular invasion, and lymph node metastasis of CSCC (all P < 0.05)." (PMID 35761838, 2022).
brain diseases (5 papers, 2022 to 2025). "This review explores the expression patterns, molecular functions, and therapeutic potential of CHI3L1 in neuroinflammatory and brain disorders." (PMID 39827337, 2025). "Recent research highlights CHI3L1 as a critical biomarker and drug target in neuroinflammatory and brain diseases, suggesting its broad applicability across a spectrum of CNS pathologies." (PMID 39827337, 2025). "As a neuroinflammatory molecule, CHI3L1 has recently gained attention in the context of brain diseases." (PMID 39827337, 2025). "CHI3L1 plays a central role in the pathology of a wide array of brain diseases, encompassing acute and chronic conditions." (PMID 39827337, 2025). "In addition to its role in disease pathology, CHI3L1 has emerged as a promising biomarker for the diagnosis and monitoring of brain disorders." (PMID 39827337, 2025). "The high expression of CHI3L1 in nearly all brain disorders may be attributed to the activation of astrocytes during disease states, leading to gliosis and exacerbating disease progression." (PMID 38003338, 2023). "Overall, CHI3L1 represents a promising therapeutic avenue, and advancing research is essential to unlocking its full potential, paving the way for treatments that could transform brain disease management and offer new hope to millions of patients worldwide." (PMID 39827337, 2025).
infectious disease (5 papers, 2012 to 2021). A disorder directly resulting from the presence and activity of a microbial, viral, or parasitic agent in humans. "Following from previous studies in non-infectious diseases showing that CHI3L1 is a biomarker for the inflammatory process, this study suggests that the potential for CHI3L1 as a biomarker for schistosome-related pathology should be explored further." (PMID 23145202, 2012).
psychiatric disease (4 papers, 2017 to 2025). "Among them, Nrf2 is a core target that co‐occurs in all three diseases (MS, AD, and psychiatric disorders), while molecules such as IL‐3 (MS, AD), TGF‐β1 (MS, ALS), C1q (AD, ALS), CHI3L1 (MS, AD), and NMDAR (psychiatric disorders, HD) play a role in both diseases." (PMID 40859959, 2025).
retinopathy (4 papers, 2011 to 2021). "However, the prognostic ability of CHI3L1 in combination with other host biomarkers should be evaluated in this group, particularly as surrogate markers for retinopathy are in development for use in clinical settings." (PMID 25047113, 2014). "CHI3L1 elevation alone is likely too non-specific to identify retinopathy-positive CM, which approximates “true” CM." (PMID 25047113, 2014).
CNS tumors (1 paper, 2015). "A total of 26 CSF proteins were identified as candidate biomarkers for neurological or psychological diseases or CNS tumors by IPA analysis, and the median inter-individual CV of these proteins was 0.177; only TTR and CHI3L1 had CVs slightly higher than 0.3." (PMID 26222143, 2015).
Diseases of the Digestive System (1 paper, 2024). "For digestive system diseases, the compound K284 alleviates lipopolysaccharide (LPS)-induced acute liver injury by inhibiting the expression of Chi3l1 and CXCL3." (PMID 39769202, 2024).